MMP2 (matrix metallopeptidase 2)
Diseases named in the same sentence as MMP2 in open-access papers (continued):
Sharing a sentence is not in itself a finding about the gene and the disease.
osteosarcoma (continued). "Given the imperative to explore novel avenues in comprehending the metastatic process in osteosarcoma, this study represents the initial endeavor to propose the potential involvement of MMP‐2 and ionic channels in the migratory and invasive behavior of osteosarcoma cells." (PMID 40079158, 2025). "Also, transwell assays were conducted to assess the influence of MMP‐2 on migration and invasion in osteosarcoma cell lines." (PMID 40079158, 2025). "While the functional activity of MMP‐2 and ionic channels has been documented, particularly in cancer cell proliferation, their specific roles in migration and invasion within the context of osteosarcoma remain understudied." (PMID 40079158, 2025). "Additionally, this study introduces a model delineating the potential interaction mechanism among ion channels, MMP‐2, and other crucial factors in the metastatic cascade of osteosarcoma." (PMID 40079158, 2025). "Moreover, the elucidated co‐participation of TTX‐sensitive NaVs and MMP‐2 in facilitating migration and invasion suggests their suitability as novel prognostic biomarkers for osteosarcoma." (PMID 40079158, 2025). "We also observed a positive correlation between NGF and MMP-2 expression in osteosarcoma tissue." (PMID 38816365, 2024). "In the present study, considering that LRP1–SNRNP25 promoted the proliferation and metastasis of osteosarcoma cells, we further found by evaluating the signaling pathways related to the invasion and migration of osteosarcoma cells that the protein levels of pJNK and MMP2 were increased." (PMID 38678020, 2024). "The current study was based on the hypothesis that MMP-2 is an important factor in the NGF-induced migration of osteosarcoma." (PMID 38816365, 2024). "In our in vitro cell experiments, we found that LRP1–SNRNP25 promotes the invasion and migration of osteosarcoma cells through the pJNK/37LRP/MMP2 signaling pathway, which can be inhibited by treatment with the pJNK inhibitor SP600125 or the MMP2 inhibitor marimastat." (PMID 38678020, 2024). "However, some studies indicate higher concentrations of MMP-2 in the blood of people with bone diseases such as osteosarcoma and osteoporosis compared to healthy individuals." (PMID 39407715, 2024). "There have been studies emphasizing that MMP-2 and MMP-9 may be considered prognostic indicators and are linked to the spread of cancer to other body parts in osteosarcoma." (PMID 39154307, 2024). "MMP-2, MMP-7, MMP-9, and MMP-14 have been linked to the progression and metastasis of osteosarcoma." (PMID 38816365, 2024). "However, our results indicate that MMP‐2 gene is an upstream mediator of a signaling pathway that regulates doxorubicin‐induced activation and phosphorylation of Src at Tyr‐416 in osteosarcoma cells." (PMID 38064181, 2023). "This also suggests that MMP‐2 regulates the expression of CHK/MATK gene in osteosarcoma." (PMID 38064181, 2023). "Thus, examining the role of intracellular/nuclear MMP‐2 in cancer cell migration pathways is crucial for developing effective osteosarcoma treatments targeting metastasis." (PMID 38064181, 2023). "High MMP-2 levels significantly induce osteosarcoma cell proliferation, invasion, and metastasis." (PMID 38031146, 2023). "However, the contribution of intracellular MMP‐2 in osteosarcoma cell migration remains largely unexplored." (PMID 38064181, 2023). "Moreover, CAFs promoted the proliferation and metastasis of osteosarcoma cells by transferring lncRNA-SNHG17 to sponge miR-2861 and then promoted MMP2 expression in osteosarcoma cells." (PMID 37377390, 2023). "The antimetastatic effect of aprepitant in osteosarcoma is probably attributed to its ability to modulate the transcriptional regulator nuclear factor kappa B (NF-κB) and, subsequently, its target genes, including MMP-2, MMP-9, and VEGF-A." (PMID 36983138, 2023).
osteosarcoma (continued). "The presence of intracellular/nuclear MMP‐2 in this context could potentially contribute to the enhanced cell migration observed in osteosarcoma cells treated with sublethal concentrations of doxorubicin." (PMID 38064181, 2023). "Moreover, it has been reported that SPAG5 contributes to metastasis of osteosarcoma by activating FOXM1/MMP2 signaling." (PMID 35342412, 2022). "MMP-2 plays a substantial role in osteosarcoma invasiveness." (PMID 32902664, 2021). "TNFAIP1 could promote proliferation by upregulating caspase-3 and downregulating NF-κB and MMP2 in osteosarcoma cells." (PMID 34344926, 2021). "Additionally, in osteosarcoma cells, it also possesses the anti-metastatic activity by down-regulating the MMP-2 and MMP-9 secretions and increasing the TIMP-1 and TIMP-2 expressions via Akt-dependent and p38 pathways." (PMID 34068885, 2021). "In summary, our study revealed that inhibition of GSK-3β might suppress the osteosarcoma invasion and migration via the pathways associated with PTEN and phosphorylation of focal adhesion kinase, followed by reduced expression of MMP-2 or MMP-9." (PMID 33969873, 2021). "Additionally, circulating MMP-2 seems to alter sensitiveness of osteosarcoma cells in chemotherapeutic drugs as a shift from MMP-9 to MMP-2 secretion is correlated with poor response to them." (PMID 32377334, 2020). "Expression of MMP2 was upregulated when MCF-7 cells were co-cultured with osteosarcoma cells." (PMID 33087801, 2020). "Furthermore, osteosarcoma-derived EVs’ treatment of fibroblasts also resulted in enhanced MMP2 and MMP9 activity as well as increased fibronectin expression." (PMID 32751693, 2020). "The expression of MMP-2 is elevated in patients with osteosarcoma, especially in those with pulmonary metastases, and could be an independent prognostic marker for the total survival time after initial diagnosis of the primary tumour." (PMID 32377334, 2020). "Although this finding still requires further investigation, we hypothesize that ADSC-secreted exosomes can induce COLGALT2 expression in osteosarcoma cells, accompanied by the downstream activation of vimentin and MMP2/9." (PMID 32523950, 2020). "Thus, the study analyzed the ability of mangiferin suppresses human metastatic osteosarcoma cell growth by down-regulating the expression of MMP-2/9 and PTHR1." (PMID 31955303, 2020). "Therefore, we measured the expression of N‐cadherin, MMP‐9 and MMP‐2 in osteosarcoma cells after BD stimulation." (PMID 31631559, 2019). "Moreover, MMP-2 and/or MMP-9 expression can be associated with the development of metastasis, poor prognosis and resistance to chemotherapy in osteosarcoma patients." (PMID 31370265, 2019). "However, in tumor tissues such as osteosarcoma, the MMP2 gene is overexpressed and contributes to the acceleration of extracellular components turnover and breakdown." (PMID 31508793, 2019). "Interestingly, blocking the TGF-β signaling pathway in osteosarcoma cells reduces the formation of lung metastases, mainly by inducing a decrease in MMP-2 expression in tumors." (PMID 29761075, 2018). "Furthermore, siRNA-mediated STAT3 inhibition in osteosarcoma cells decreased cell proliferation and invasion and down-regulated MMP2/9 expression." (PMID 28423603, 2017). "In osteosarcoma patients, MMP-2 and MMP-9 are generally overexpressed." (PMID 29340064, 2017). "In addition, we showed that baicalein suppressed osteosarcoma cells adhesion, migration, and invasion by decreasing the expression and activity of MMP-2 and MMP-9." (PMID 29156780, 2017). "Connective tissue growth factor (CTGF) could promote osteosarcoma cells metastasis through the elevation of MMP-2 and MMP-3." (PMID 28938584, 2017). "In order to delineate the mechanisms underlying downregulation of MMP9 and MMP2 after PC4 knockdown, and to confirm that these results were not restricted to the 143B tumor cell line, we measured fibronectin mRNA levels in seven osteosarcoma cell lines after PC4 knockdown." (PMID 28881805, 2017).
osteosarcoma (continued). "Strong overall MMP activities could be detected in osteosarcoma pretreatment biopsies with MMP2 and MMP9 as predominant active MMPs." (PMID 26979530, 2016). "In contrast to MMP9, several studies observed a more important role of MMP2 in osteosarcoma." (PMID 26979530, 2016). "Further, analysis of osteosarcoma cells isolated from 23 pretreatment tumor tissues showed high MMP2 levels in all samples, while MMP9 could only be detected in one sample." (PMID 26979530, 2016). "However, the role of FAK in MMP-2 activation of osteosarcomas should be further investigated in future work." (PMID 25605016, 2015). "We therefore examined whether the Akt and MAPK pathways are involved in RESV-mediated suppression of cell motility and MMP-2 expression in osteosarcoma cells." (PMID 25605016, 2015). "Studies have shown that resveratrol could suppress the osteosarcoma cell invasion and migration in vitro as well as lung metastasis in vivo by inhibiting MMP-2 activation." (PMID 26305257, 2015). "Interestingly, a previous report indicated that all osteosarcoma cells from tissue specimens and established cell lines were found to express MMP-2, but pro-MMP-9 was detected in only one tissue sample and one cell line (U-2OS)." (PMID 25605016, 2015). "Our results echo previous findings which indicated that MMP-2 might be an important regulator of tumor metastasis in osteosarcomas." (PMID 25605016, 2015). "Moreover, the activity of MMP-2 was abolished in osteosarcoma cells with suppressed EFEMP1 expression." (PMID 25987128, 2015). "Moreover, we also observed that the miR-328 expression level in osteosarcoma tissues was lower than that in normal bone tissues and was inversely correlated with the expression level of MMP-2 in osteosarcoma tissues." (PMID 25605016, 2015). "A qRT-PCR analysis of MMP2 and miR-328 performed in osteosarcoma and normal samples, showed inverse expression levels of MMP2 and miR-328 between osteosarcoma and normal bone tissues, and a significant negative correlation between MMP-2 and miR-328 was observed in osteosarcomas." (PMID 25605016, 2015). "Moreover, gelatin zymography was conducted to examine the activity of MMP-2 in the conditioned medium of treated osteosarcoma cells." (PMID 25987128, 2015). "In our laboratory, we also found that bufalin suppressed the migration and invasion of human osteosarcoma U-2 OS cells by suppression of the matrix metalloproteinase-2 (MMP-2), extracellular signal-regulated kinase (ERK), and c-Jun N-terminal kinase (JNK) signaling pathways." (PMID 22719785, 2012). "While the downstream effectors of metastasis in the genetically engineered models remain unknown, evidence presented here implicates upregulation of an NFAT → MMP-2 pathway in the development of metastatic osteosarcoma." (PMID 20107604, 2010). "Inhibition of either MMP-2 or NFAT inhibited invasion by Czech-II/Ei osteosarcoma cells." (PMID 20107604, 2010). "Therefore, pJNK and MMP2 may function as signaling molecules downstream of LRP1–SNRNP25 to influence the biological behavior of osteosarcoma cells." (PMID 38678020, 2024). "Thus, knocking out the MMP‐2 gene in osteosarcoma cells, in the presence of active extracellular MMP‐2, results in a significant inhibition of cancer cell migration, suggesting that the MMP‐2 gene, rather than extracellular protein, plays a major role in cancer cell migration pathways." (PMID 38064181, 2023). "Thus, inhibition of GSK-3β may suppresses osteosarcoma cell migration and invasion by reducing the expressions of MMP-2 and MMP-9." (PMID 33969873, 2021). "We speculate that the inhibition of MMP-2/9 is key mechanism for the inhibition of osteosarcoma." (PMID 31955303, 2020). "Therefore, our study shows that KMT2C could be involved in ECM modifications that lead to metastatic progression and it could regulate the MMP2 activity in osteosarcoma progression." (PMID 30093974, 2018).
osteosarcoma (continued). "Consequently, ADSCs in adipose tissue may increase osteosarcoma cell proliferation and metastasis in conjunction with changes in MMP2/9 and E-cadherin expression, which are at least partially mediated by the activation of the STAT3 signalling pathway." (PMID 28423603, 2017). "Moreover, AEG-1 plays a crucial role in osteosarcoma progression through MMP-2." (PMID 25987128, 2015). "In addition to RESV-mediated transactivation inhibition of the MMP-2 gene, we further investigated which miRNAs might be involved in RESV-mediated MMP-2 gene expression and cell motility in osteosarcoma cells." (PMID 25605016, 2015). "Finally, we investigated the clinical importance of MMP-2 and miR-328 in osteosarcoma patients." (PMID 25605016, 2015). "Therefore, other factors, such as matrix metalloproteinase-9 (MMP-9), MMP-2, and vascular endothelial growth factor, may also be involved in promoting the proliferation and invasion of osteosarcoma cells." (PMID 25890096, 2015). "In addition to HOS cells, MMP-2 protein and enzyme activity were also concentration-dependently suppressed by RESV in two other osteosarcoma cell lines, 143B and U2OS, suggesting that suppression of MMP-2 by RESV may be a general phenomenon in osteosarcoma." (PMID 25605016, 2015). "This aligns with previous studies reporting that WISP1 promotes MMP2 and MMP9 expression in chondrosarcoma and osteosarcoma cells, thereby facilitating motility and invasion." (PMID 41597235, 2026). "The elevated activity of these type IV collagenases (MMP-2 and MMP-9) is recognized as a key contributor to tumor progression and dissemination in several malignancies, including osteosarcoma." (PMID 40869275, 2025). "This further disrupts F-actin remodeling and suppresses the activities of MMP2, MMP14, and the cleavage of Ln5γ2, demonstrating the inhibition of VM in osteosarcoma cells by targeting the miR-520d-3p/MIG-7/PI3K/MMPs/Ln5γ2 signaling axis." (PMID 41019994, 2025). "PPEE inhibits VM formation in osteosarcoma both in vitro and in vivo by downregulating the expression of FAK and migration-inducing gene 7 (MIG-7), suppressing the activities of MMP2 and MMP9, and reducing the number of CD31-/PAS+ channels in vivo." (PMID 41019994, 2025). "For example, in an osteosarcoma cell line study, RUNX2 silencing inhibited invasion capacity by suppressing VEGF, MMP-2, and MMP-9 expression." (PMID 40806771, 2025). "MMP overexpression (specifically MMP-2, MMP-9, or MMP-13) is a promising indicator for prognosis and pulmonary metastasis in osteosarcoma." (PMID 38816365, 2024). "For example, CAFs expressing MMP-2 and MMP-9 have been identified in osteosarcoma, and their increased presence in the tumor area has been associated with MMP-2 and MMP-9 expression." (PMID 38542199, 2024). "In cellular experiments using human osteosarcoma cells (143B and MG63), NGF upregulated MMP-2 expression and promoted wound healing, cell migration, and cell invasion." (PMID 38816365, 2024). "Glabridin inhibits osteosarcoma cell migration and invasion by suppressing p38 and JNK pathway activation, preventing CREB-AP1 complex formation, and reducing MMP-2 and MMP-9 expression." (PMID 39723390, 2024). "SPAG5 silencing inhibited migration, invasion, and epithelial-mesenchymal transition of osteosarcoma cells, which is attributed to regulating the FOXM1/MMP2 axis." (PMID 38807081, 2024). "It was established that the MMP2 gene acts as an upstream regulator of Src kinase activity by inhibiting its endogenous suppressor, CHK/MATK, in osteosarcoma cells." (PMID 39358756, 2024). "In summary, NGF is positively correlated with MMP-2 in human osteosarcoma tissue and NGF promotes osteosarcoma cell metastasis by upregulating MMP-2 expression." (PMID 38816365, 2024). "Four ARGs-BRMS, COL4A2, FGF2, and OGT-were used to develop an RFS-predicting model, whereas seven ARGs-CD24, FASN, MMP2, EIF2AK3, ID2, PPARG, and PIK3R3-were used to develop an OS-predicting model in patients with osteosarcoma." (PMID 38217543, 2024).
osteosarcoma (continued). "MMP13, MMP2, and MMP14 have been identified to interact with each other and to promote the progression and invasion of osteosarcoma." (PMID 38966281, 2024). "In our work, the degradation of the here used Mg-based materials led to an increased secretion of MMP-2 and MMP-9 and suggested an increased invasion and metastatic capability of osteosarcoma cells under the impact of those materials." (PMID 35600975, 2023). "In this study, we reveal that the MMP‐2 gene acts as an upstream regulator of Src kinase activity by suppressing its endogenous inhibitor, CHK/MATK, in osteosarcoma cells." (PMID 38064181, 2023). "Clinically, we anticipate that inhibiting intracellular/nuclear MMP‐2 and allowing CHK/MATK re‐expression will enhance the effectiveness of sublethal doxorubicin treatments in osteosarcoma patients." (PMID 38064181, 2023). "This study demonstrates that the MMP‐2 gene regulates Src kinase activity by suppressing CHK/MATK, an endogenous inhibitor of Src, in osteosarcoma cells." (PMID 38064181, 2023). "To investigate MMP‐2′s role in regulating the expression of endogenous Src inhibitors Csk and CHK/MATK in osteosarcoma, we analyzed gene fold expression and protein levels in U2OS WT and MMP‐2 KO cells." (PMID 38064181, 2023). "Our study is the first to demonstrate that ononin has anti-osteosarcoma activity against MG-63 and U2OS cells, and MG-63- xenograft mice by limiting the expression of MMP2/9." (PMID 36765716, 2023). "We also found that MMP‐2 regulates Src kinase activity via suppression of the endogenous Src inhibitor, CHK/MATK, in osteosarcoma cells." (PMID 38064181, 2023). "In osteosarcoma, COX-2 affects the expression levels of vimentin, E-cadherin, MMP-9 and MMP-2 by activating the PI3K/AKT/NF-κ b signaling pathway, leading to a significant increase in the migratory ability of osteosarcoma cells." (PMID 37404761, 2023). "According to research, STK39 dysregulation affects MMP2 (matrix metallopeptidase 2) and MMP9 (matrix metallopeptidase 9), thus actively participating in osteosarcoma." (PMID 36005137, 2022). "For example, in osteosarcoma cells, RAP2 enhances cell migration and invasion via increasing MMP2 and MMP9 expression." (PMID 35538031, 2022). "Recent research has shown new intracellular locations for MMP-2 and MT1-MMP in various cell types, including cardiomyocytes, megakaryocytes/platelets, retina, immune cells, osteosarcoma, and other cancer cells." (PMID 36076910, 2022). "Altogether, these results suggest that aprepitant can modulate the invasive behavior of human osteosarcoma cells, possibly by regulating both the expression and activities of MMP-9 and MMP-2." (PMID 36177059, 2022). "The expression of mesenchymal marker Vimentin and the matrix metalloproteinase 2 (MMP-2) which degrades and remodels the extracellular matrix (ECM) was increased in most of the osteosarcoma cell lines." (PMID 36344502, 2022). "An in vitro study reported that seahorse hydrolysate has ameliorative effects on MG-63 osteosarcoma cells by reducing matrix metalloproteinases (MMPs), such as MMP-1 and MMP-2." (PMID 35509713, 2022). "We observed that EMMPRIN knockdown inhibited the secretion of MMP2, the expression of VEGF, and invasion and metastasis of osteosarcoma." (PMID 34565336, 2021). "We found that cordycepin significantly reduced the protein expression levels of Bcl-2, MMP-2, and MMP-9 and induce increased the expression levels of Bax, and Cleaved PARP in osteosarcoma cells." (PMID 34953496, 2021). "Treatment of osteosarcoma cells with FLLL32 decreased the expression of survivin, VEGF, and MMP2 at both mRNA and protein levels with a concomitant decrease in STAT3 levels." (PMID 34671398, 2021). "MMP-2 and MMP-9 are highly expressed in osteosarcoma tissues, and they play important roles in the invasion and metastasis of tumor cells." (PMID 33969873, 2021).